TRBV14 (T cell receptor beta variable 14)
Description:
V region of the variable domain of T cell receptor (TR) beta chain that participates in the antigen recognition. Alpha-beta T cell receptors are antigen specific receptors which are essential to the immune response and are present on the cell surface of T lymphocytes. Recognize peptide-major histocompatibility (MH) (pMH) complexes that are displayed by antigen presenting cells (APC), a prerequisite for efficient T cell adaptive immunity against pathogens. Binding of alpha-beta TR to pMH complex initiates TR-CD3 clustering on the cell surface and intracellular activation of LCK that phosphorylates the ITAM motifs of CD3G, CD3D, CD3E and CD247 enabling the recruitment of ZAP70. In turn ZAP70 phosphorylates LAT, which recruits numerous signaling molecules to form the LAT signalosome. The LAT signalosome propagates signal branching to three major signaling pathways, the calcium, the mitogen-activated protein kinase (MAPK) kinase and the nuclear factor NF-kappa-B (NF-kB) pathways, leading to the mobilization of transcription factors that are critical for gene expression and essential for T cell growth and differentiation. The T cell repertoire is generated in the thymus, by V-(D)-J rearrangement. This repertoire is then shaped by intrathymic selection events to generate a peripheral T cell pool of self-MH restricted, non-autoaggressive T cells. Post-thymic interaction of alpha-beta TR with the pMH complexes shapes TR structural and functional avidity.
Synonyms: TCRBV14S1; TCRBV16S1A1N1
Tractability: Antibody: UniProt places it where antibodies can reach, with medium confidence; UniProt predicts a signal peptide or a membrane-spanning region; its Gene Ontology location is reachable by antibodies, with medium confidence.
Gene: T-cell receptor variable (V) gene on chromosome 7 (142,587,868 to 142,588,359, forward strand). Ensembl gene ENSG00000275743.
Subcellular location: Cell membrane
Gene Ontology:
Biological process: cell surface receptor signaling pathway
Cellular component: plasma membrane
Homologues: Orthologues: macaque TRBV14 (90% identical). Paralogues in human: TRBV7-2 (57% identical), TRBV12-4 (55% identical), TRBV11-1 (53% identical), TRBV11-2 (53% identical), TRBV12-3 (53% identical), TRBV7-3 (53% identical), TRBV7-6 (52% identical), TRBV11-3 (51% identical), TRBV12-5 (51% identical), TRBV17 (50% identical), TRBV7-7 (50% identical), TRBV7-1 (49% identical), and 39 more.
Diseases named in the same sentence as TRBV14 in open-access papers:
TRBV14 is named in the same sentence as 3 diseases in open-access papers, as found by Europe PMC text mining. Sharing a sentence is not in itself a finding about the gene and the disease.
TRBV14 shares sentences with these, for which no sentence is quoted: cancer (1 paper); COVID-19 (1); infection (1).